MYBPC1 (myosin binding protein C1)
Description:
Thick filament-associated protein located in the crossbridge region of vertebrate striated muscle a bands. Slow skeletal protein that binds to both myosin and actin. In vitro, binds to native thin filaments and modifies the activity of actin-activated myosin ATPase. May modulate muscle contraction or may play a more structural role.
Synonyms: MYBPCS; ssMyBP-C; CMYO16; CMYP16; LCCS4; MYBPCC; MYOTREM
Tractability: No criterion of Open Targets' tractability assessment is met for any kind of drug.
Gene: Protein-coding gene on chromosome 12 (101,568,353 to 101,686,181, forward strand). Ensembl gene ENSG00000196091.
Pathways (Reactome):
Muscle contraction: Striated Muscle Contraction
Gene Ontology:
Molecular function: myosin binding; protein binding; structural constituent of muscle; titin binding
Biological process: sarcomere organization
Cellular component: cytosol; M band; myofibril
Genetic constraint (gnomAD): Loss-of-function variants: 48 observed, 141.07 expected, observed/expected ratio (o/e) 0.34, 90% interval 0.27 to 0.43. The upper end of that interval is the gene's LOEUF score, 0.43, which puts it in group 1 of 6, group 1 being the genes least tolerant of losing a copy. Missense variants: 1,186 observed, 1,462.8 expected, observed/expected ratio (o/e) 0.81, 90% interval 0.77 to 0.85. Synonymous variants: 465 observed, 489.82 expected, observed/expected ratio (o/e) 0.95, 90% interval 0.88 to 1.02.
Homologues: Orthologues: chimpanzee MYBPC1 (97% identical), macaque MYBPC1 (96% identical), rat Mybpc1 (92% identical), pig MYBPC1 (92% identical), dog MYBPC1 (91% identical), rabbit MYBPC1 (91% identical), guinea pig MYBPC1 (89% identical), mouse Mybpc1 (88% identical), tropical clawed frog mybpc1 (73% identical), zebrafish mybpc1 (65% identical), Caenorhabditis elegans C34F6.10 (15% identical), Drosophila melanogaster mtgo (12% identical). Paralogues in human: MYBPC3 (49% identical), MYBPC2 (48% identical), IGSF22 (25% identical), MYBPH (20% identical), MYOM1 (19% identical), MYOM2 (18% identical), MYOM3 (18% identical), OBSL1 (18% identical), MYBPHL (15% identical), FNDC3B (15% identical), FNDC3A (14% identical).
Diseases named in the same sentence as MYBPC1 in open-access papers:
MYBPC1 is named in the same sentence as 30 diseases in open-access papers, as found by Europe PMC text mining. Sharing a sentence is not in itself a finding about the gene and the disease. The quoted sentences say what the papers report.
distal arthrogryposis type 1 (8 papers, 2012 to 2026). "Of these genes, mutations in the gene encoding myosin binding protein C slow MYBPC1 were recently identified in two families with distal arthrogryposis type 1B." (PMID 25679999, 2015). "Mutations in MYBPC1 encoding slow-skeletal MyBP-C (ssMyBP-C) have recently been implicated in a disease of skeletal muscle—distal arthrogryposis type 1 (DA-1)—characterised by congenital contracture of distal limbs." (PMID 22415774, 2012). "For example, one study found that MYBPC1 mutations W236R and Y856H could cause distal arthrogryposis type 1." (PMID 35832193, 2022). "The significance of MYBPC1 has not been fully determined, though mutations in this gene are associated with type 1 distal arthrogryposis." (PMID 24023788, 2013).
prostate carcinoma (5 papers, 2013 to 2022). A carcinoma that arises from epithelial cells of the prostate gland. "For example, MYBPC1, UBE2C and NUSAP1 have been previously reported to be differentially expressed throughout prostate cancer progression." (PMID 23826159, 2013). "Furthermore, authors revealed such genes for the TMPRSS2-ERG prostate cancer molecular subtype (B4GALNT4, ASRGL1, MYBPC1, RGS11, SLC6A14, GALNT13 and ST6GALNAC1)." (PMID 36077746, 2022). "Additionally, we revealed such genes for the TMPRSS2-ERG prostate cancer molecular subtype (B4GALNT4, ASRGL1, MYBPC1, RGS11, SLC6A14, GALNT13, and ST6GALNAC1)." (PMID 31447885, 2019). "Notably, one group of genes with very strong negative correlations (≤-0.9) to radiomic features were found to be associated with the AR signaling genes: KLK2, KLK3, HOMER2, BMPR1B, or belong to validated prostate cancer classifiers: CHRNA2, MT1H, DPP4, MYBPC1." (PMID 27438142, 2016).
congenital myopathy (4 papers, 2025 to 2026). "Pathogenic variants in MYBPC1, the gene encoding the slow skeletal isoform of Myosin Binding Protein-C (sMyBP-C), are linked to a newly recognized form of congenital myopathy termed Myotrem (OMIM #618524)." (PMID 40508067, 2025). "Dominant missense mutations in MYBPC1, the gene encoding the essential sarcomeric slow Myosin Binding Protein-C (sMyBP-C), are associated with Myotrem, a new, early-onset congenital myopathy characterized by muscle weakness, hypotonia, skeletal deformities, and myogenic tremor." (PMID 40569690, 2025). "Pathogenic variants in MYBPC1, the gene encoding the slow skeletal isoform (sMyBP-C), lead to a dominant congenital myopathy, termed Myotrem, characterized by muscle weakness, hypotonia, and a distinctive tremor of myogenic origin, in the absence of neuropathy." (PMID 40508067, 2025).
myogenic tremor (4 papers, 2021 to 2025). "Dominant missense variants of MYBPC1, the gene encoding sMyBP-C, are linked to a new myopathy termed Myotrem (OMIM #618524), associated with tremor." (PMID 40508067, 2025). "We also highlight conditions such as neuropathic tremor, pseudoathetosis, and MYBPC1-associated myogenic tremor as examples of PIMD." (PMID 37008994, 2023). "Using CRISPR/Cas9 technology, we generated a KI mouse model carrying the MYBPC1 E248K pathogenic variant, which is causatively linked to generalized myopathy with myogenic tremors in both male and female members of a Latvian family." (PMID 34437302, 2021). "Pathogenic MYBPC1 variants have been previously associated with the development of severe and lethal forms of arthrogryposis multiplex congenita and, more recently, with a new myopathy referred to as Myotrem." (PMID 40569690, 2025). "Given the absence of neuropathy in individuals with Myotrem, and the restricted expression of MYBPC1 in skeletal muscle, this characteristic tremor is believed to originate within the muscle itself." (PMID 40508067, 2025).
arthrogryposis multiplex congenita (2 papers, 2015 to 2025). Arthrogryposis multiplex congenita (AMC) is a group of disorders characterized by congenital limb contractures. "Our results expand the phenotypic spectrum of MYBPC1-related arthrogryposis multiplex congenita (AMC)." (PMID 25679999, 2015). "Our results expand the phenotypic spectrum of MYBPC1-related arthrogryposis multiplex congenita (AMC) and we speculate that the domain C2 of MYBPC1 may play an important role in binding to S2 fragment of myosin." (PMID 25679999, 2015).
familial hypertrophic cardiomyopathy (2 papers, 2016 to 2021). Hypertrophic cardiomyopathy caused by mutations in the genes encoding components of the sarcomere, in the absence of predisposing conditions. "MYBPC1 appears to be a novel gene responsible for DA1, though the mechanism of disease may differ from how some cardiac MYBPC3 mutations cause hypertrophic cardiomyopathy." (PMID 34356068, 2021).
gynecological cancer (2 papers, 2017 to 2023). "Our approach has identified “actin (ACTA1)” and “myosin (MYH7)” combination with “MYBPC1” as the potential pathways causing promoter changes in gynecological cancers." (PMID 28927463, 2017). "Expression of ACTA1, MYH7, and MYBPC1 may be a potential promotor of gynecological cancer initiation or progression." (PMID 38248716, 2023).
muscular dystrophy (2 papers, 2019 to 2022). Muscular dystrophy (MD) refers to a group of more than 30 genetic diseases characterized by progressive weakness and degeneration of the skeletal muscles that control movement. "Many of the differentially expressed genes have been associated with muscular dystrophy (i.e., Mybpc1 and Dmpk)." (PMID 36123393, 2022).
neuropathy (2 papers, 2021 to 2025). A disorder affecting the nervous system that manifests with pain, tingling, numbness, and/or muscle weakness. "Recently, our group described the causal association of dominant missense pathogenic variants in MYBPC1 with an early-onset myopathy characterized by generalized muscle weakness, hypotonia, dysmorphia, skeletal deformities, and myogenic tremor, occurring in the absence of neuropathy." (PMID 34437302, 2021).
arthrogryposis (1 paper, 2015). A rare, non-progressive congenital disorder characterized by multiple joint contractures which are present at birth. "More importantly, dominant negative effects of human DA1 MYBPC1 missense mutations on muscle function have been demonstrated in zerbrafish models of arthrogryposis." (PMID 25679999, 2015).
breast carcinoma (1 paper, 2019). "Increased expression of MYBPC1 gene was observed in breast cancer." (PMID 31447885, 2019).
cardiomyopathies (1 paper, 2022). "Distal Arthrogryposis has been attributed to pathogenic variants in MYBPC1, and MYBPC3 is known to cause a series of cardiomyopathies, including HCM, DCM and congenital heart defects." (PMID 35832193, 2022).
lobular carcinomas (1 paper, 2007). "Several genes encoding proteins involved in actin, calcium and metal ion binding were downregulated (MYBPC1, DST, PIP, CA2), and some genes with the same function (BGN, ADAM12) were upregulated in lobular carcinomas." (PMID 17389037, 2007).
melanoma (1 paper, 2020). A malignant, usually aggressive tumor composed of atypical, neoplastic melanocytes. "Next, we validated the highest significantly down- (Myh2, Mybh, Sypl2, Xirp1, Mybpc1) and up- (Fcgbp, Areg) regulated genes, including the melanoma-specific genes (Dmnt1 and Nrp2) identified by RNA sequencing following treatment with SAM+anti-PD-1 by RT-qPCR." (PMID 32983966, 2020).
skeletal myopathies (1 paper, 2022). "Mutations in the MYBPC family of genes, including slow skeletal (MYBPC1), fast skeletal (MYBPC2) and cardiac (MYBPC3), can result in cardiac and skeletal myopathies." (PMID 35832193, 2022).
tuberculosis (1 paper, 2022). A chronic, recurrent infection caused by the bacterium Mycobacterium tuberculosis. "The present study aimed to evaluate the diagnostic utility of creatine kinase-MB (CK-MB), hepcidin (HEPC), phospholipase A2 group IIA (PLa2G2A), and myosin-binding protein C (MYBPC1) for tuberculosis (TB)." (PMID 35133607, 2022).
urothelial carcinoma (1 paper, 2020). A malignant neoplasm derived from the transitional epithelium of the urinary tract (urinary bladder, ureter, urethra, or renal pelvis). "Using high-through sequencing of tumor DNA obtained from urothelial carcinoma, the researchers identified the integration site of the BKV genome into exon 26 of myosin-binding protein C1 gene (MYBPC1) on chromosome 12 in tumor cells but not in normal renal cells." (PMID 32872288, 2020).
myopathy (11 papers, 2015 to 2026). A disease of the muscle in which the muscle fibers do not function properly. "Our group has recently identified pathogenic variants in MYBPC1 whose monoallelic presence leads to a new myopathy characterized by tremor, known as Myotrem myopathy (NIH concept ID: C5231401) or congenital myopathy-16 (CMYP16)." (PMID 40569690, 2025). "To mechanistically interrogate the etiologies of this MYBPC1-associated myopathy in vivo, we generated a knock-in mouse model carrying the E248K pathogenic variant." (PMID 34437302, 2021). "It is only recently, however, that mutations in MYBPC1 have been directly associated with inherited myopathies, and specifically with severe and lethal forms of distal arthrogryposis myopathy." (PMID 27683561, 2016). "We recently reported compound heterozygote mutations in MYBPC1, leading to a DA1-like myopathy with muscle weakness, feeding difficulties requiring nasogastric tube feeding, and spinal rigidity with tremor." (PMID 40268053, 2025). "Our findings are, therefore, highly impactful in establishing not only a new form of MYBPC1 myopathy, but of a myopathy encompassing several genes that likely originates from structurally disordered and dysregulated sarcomeres." (PMID 34437302, 2021). "Given the recent involvement of MYBPC1 in severe and lethal myopathies, we predict that a comprehensive, multidisciplinary evaluation of its regulation and roles in health and disease is in order." (PMID 27683561, 2016). "Interestingly, all of these genes are associated with genetic (cardio)myopathies in humans (TTN, NEB, MYBPC1, TNNT3 and TPM1) or mice (PDLIM3)." (PMID 37000196, 2023). "Thus, it can be concluded that the MYBPC1 gene leads to severe and lethal myopathies." (PMID 35132338, 2022).
tumor (5 papers, 2016 to 2023). "MYBPC1 encodes a member of the myosin-binding protein C family, which may be expressed primarily in non-tumor cells in the TME." (PMID 37205181, 2023). "When gene expression in high grade cancers was compared to that of low grade tumours, the expression of 20 of 25 genes tested were lower in higher grade tumours, and reached statistical significance for twelve, including KLK3 and MYBPC1." (PMID 27120785, 2016). "Unfortunately, there are no in vitro studies on the role of the MYBPC1 gene in tumor metastasis." (PMID 35132338, 2022).
cancer (2 papers, 2016 to 2020). A tumor composed of atypical neoplastic, often pleomorphic cells that invade other tissues. "Moreover, TNNT3 and MYBPC1 tend to be correlated with ANT1 in RMS patients (R2 cancer analysis, Davicioni E-TABM-1202 dataset)." (PMID 32728477, 2020).
infection (1 paper, 2024). The state of being infected such as from the introduction of a foreign agent such as serum, vaccine, antigenic substance or organism. "Genes encoding protein components of the cytoskeleton (NEB, MYOM2, MYOZ1, and MYBPC1) and surfactant proteins (A1, C, and D) were among the most significantly downregulated genes upon infection with swH1N1." (PMID 39247193, 2024).
musculoskeletal disorders (1 paper, 2024). "We observed that MYH7, RYR1, FBN1, TNNT1, MYBPC1, COL1A1, and CHRNB1 were related to musculoskeletal disorders." (PMID 38658807, 2024).
MYBPC1 also shares sentences with these, for which no sentence is quoted: Lethal Congenital Contractural Syndrome-4 (3 papers); Tremor (3); diabetes (1); distal arthrogryposis (1); Hypertension (1); Lethal congenital contracture syndrome 4 (1); osteosarcoma (1); polymyositis (1).